CSF3 (colony stimulating factor 3)
Diseases named in the same sentence as CSF3 in open-access papers (continued):
Sharing a sentence is not in itself a finding about the gene and the disease.
tumor (continued). "In response to CSF3, neutrophils upregulate the expression of BV8 (also known as prokineticin-2) that induce myeloid cell mobilization and myeloid-dependent tumor angiogenesis." (PMID 29675018, 2018). "By contrast, tumor tissues from PyMT-B6 and KPC models had higher Csf3 levels compared to normal mammary and pancreas tissues." (PMID 29593283, 2018). "The coordinated downregulation of KLF4, OLR1, CSF3, WIF1, RAMP3, and AGER, may impair tumor-suppressive mechanisms, thereby facilitating cancer progression, including enhanced tumor growth, migration, invasion, and metastasis." (PMID 40797277, 2025). "In contrast, this study demonstrates a different mechanism in which CSF3 directly regulates tumor cells rather than acting on MDSCs." (PMID 40185722, 2025). "Our study demonstrated that CSF3 neutralizing antibody could significantly reduce oHSV-induced NETosis within the TME and tumor survival." (PMID 38167409, 2024). "However, this triggers an overall rise in m6A levels in infected tumor cells via the IGF2BP3/MIB1/FTO feedback loop, ultimately leading to CSF3-mediated NETosis." (PMID 38167409, 2024). "Addition of exogenous CSF3 significantly increased NETosis and diminished the effectiveness of BET inhibition in reducing NETosis and inhibiting tumor survival in both TAN and induced neutrophil models." (PMID 38167409, 2024). "Additionally, GPR35+ MDSC colonization to the lung was promoted in a lung metastasis model of breast cancer via the tumor secretion of CXCL17 and CSF3." (PMID 37566060, 2023). "We initially examined CSF3 and PDCD1 expression in diverse tumor tissue against normal tissue, revealing that PDCD1 expression was greater in the majority of tumor tissue versus unpaired/paired normal tissue, whereas CSF3 expression was lower in the majority of tumor tissue." (PMID 37644514, 2023). "Moreover, tumor-secreted cytokines like CXCL8, PDGF, MIP1 and CSF3 increase the mobilization of neutrophils from the bone marrow and spleen, leading to an elevated neutrophil-to-lymphocyte ratio in both human and mouse studies." (PMID 37566060, 2023). "Human cancer cell lines secrete cytokines able to impair macrophage anti-tumor properties, i.e., IL-10, TGF-β, and PGE2 stimulate myelopoiesis, producing granulocyte and macrophage growth factors, i.e., M-CSF (CSF-1), GM-CSF (CSF-2), and G-CSF (CSF-3)." (PMID 34680425, 2021). "CSF3 is an important regulator of CRC, increasing pro-tumor behavior in tumor and immune cells." (PMID 33606788, 2021). "Higher tumor or nodal stages did not demonstrate significant enrichment of CSF3 or CSF3R expression, which was surprising given that smaller studies have found higher expression of both ligand and receptor in higher T and N stage patients." (PMID 33606788, 2021). "The role that CSF3 and CSF3R play in the evolution of the CRC tumor microenvironment may offer a potential therapeutic target and should be further explored." (PMID 33606788, 2021). "Moreover, the ALA-PALE region was characterized by an overexpression, with respect to both ALA+ and ALA−derived GASC, of CCL20, CSF3 and IL1B (magenta box), suggesting the possible importance of these three genes in the infiltrating front of the tumor." (PMID 33066172, 2020). "Consequently, pharmacological or genetic blockade of CSF3, CSF3R, or BV8 decreased the number of TANs and inhibited tumor angiogenesis and growth." (PMID 31572387, 2019). "We also observed that the majority of the Csf3 ISH signal was present in the tumor cells and not the stroma." (PMID 29593283, 2018). "In another study, increased glutamine consumption within tumor cells was found to promote recruitment and generation of MDSC to the tumor by stabilizing the expression of the transcription factor laryngeal adductor paralysis (LAP) and increasing expression of colony stimulating factor 3 (CSF3)." (PMID 39796781, 2025).
tumor (continued). "Since Csf3 participates in MDSC recruitment and tumor promotion in multiple tumor models, this difference may contribute to the observations with MHV68-infected tumor-bearing mice shown here." (PMID 39338937, 2024). "Forced expression of Csf3 had no impact on primary tumour growth." (PMID 34836954, 2021). "However, in an experiment in which the injected cancer cells were engineered to express colony-stimulating factor 3 (Csf3; also known as GCSF), neutrophils could promote tumor regression." (PMID 31932292, 2020). "Csf3 levels in the serum were not significantly different between groups, but a potential modest increase (1.8-fold, p = 0.06, ANOVA) in infected tumor-bearing mice appeared to be reduced (1.3-fold, p = 0.45, ANOVA) in infected wild-type mice." (PMID 39338937, 2024).
infection (720 papers, 2004 to 2026). The state of being infected such as from the introduction of a foreign agent such as serum, vaccine, antigenic substance or organism. "In addition, CCR5-deficiency during infection affected the upregulation of cytokine genes such as Csf2, Csf3, Cxcl1, Edn1, and Il6 and other genes associated with immune response (i.e., Gimap6, Mcoln2) and migration (i.e., Cyfip2)." (PMID 31506064, 2019). "Expression of CSF3 (colony-stimulating factor 3) links immune activation, epithelial integrity, and cell survival during infection, playing a dual role in both host defense and tissue damage modulation." (PMID 40634947, 2025). "Cluster 0 myeloid cells emerged as a prominent population post‐PA infection, characterized by the expression of Il12a, Il1a, Ccl4, and Csf3 genes, indicative of a pro‐inflammatory M1‐like phenotype." (PMID 40087815, 2025). "In this model of lung tumor promotion by MHV68, induction of Csf3 requires both the infection and the presence of lung tumors." (PMID 39338937, 2024). "For G-CSF, production is stimulated in response to so-called ‘emergency’ signals, such as inflammation or infection, that greatly elevate expression of the cognate CSF3 gene in various cells." (PMID 38254802, 2024). "Both types of mice displayed infection-related increases (wild-type 5.4-fold, K-RasLA1 6-fold) in the levels of Csf3 mRNA in the lung." (PMID 39338937, 2024). "Assessment of cytokines in the lung revealed that expression of Type 17 cytokines (Il-6, Cxcl1, Csf3) peaked at day 7 post-infection." (PMID 39338937, 2024). "K-RasLA1 and wild-type mice were infected with 40,000 pfu of MHV68 or mock-infected and harvested 7 days post-infection, a time of peak expression of Il-6, Csf3, and Cxcl1 mRNAs." (PMID 39338937, 2024). "The top predicted transcriptional regulators (P < .01) at 2 h post-infection were wortmannin, CSF3 which is predicted to be activated, LEP, JNK, and, IL5 which are predicted to be inhibited." (PMID 33382951, 2021). "CSF2 and CSF3 respond to infection by inducing inflammation and recruiting lymphocytes to the site of infection." (PMID 34358063, 2021). "They demonstrated that the KO mice were defective in recruitment of CD11bHigh Ly6GHigh neutrophils, chemoattractants, and stabilizing factors like CXCL1, CXCL2, CCL3, and CSF3 to the site of infection in the colon." (PMID 34724858, 2021). "During infection, CSF3 works along with IL3, IL6, and CSF2 to stimulate neutrophil granulopoiesis in the bone marrow to restore neutrophil homeostasis." (PMID 33362771, 2020). "Of these genes, SAA2 was the most significant (-10logp-value of 81); the distinctive genes in the SARS-CoV-2’s infection response were CSF3, CSF2, IL1B, and PTGS2." (PMID 33301474, 2020). "This suggests that under certain conditions; such as infection, CSF3 can extend the lifespan of a mature neutrophil." (PMID 33236983, 2020). "Age-exacerbated bacterial growth and delayed wound healing in experimental infection have been successfully treated with exogenous CSF3 to enhance neutrophil recruitment." (PMID 31936467, 2020). "Despite their minor role in T. marneffei conidial phagocytosis, neutrophil numbers increased during infection from a protective CSF3-dependent granulopoietic response." (PMID 29883484, 2018). "Granulocyte colony-stimulating factor (G-CSF or CSF3) was the most up-regulated eukaryotic gene during infection with a fold change of 706.23 (p = 8.93 × 10−104)." (PMID 27982111, 2016). "The qPCR results revealed that the well-known Mtb-activated genes Tnf, Csf3, Nos2 and Il10 were upregulated at 6 h and 24 h post-infection, and the fold changes at 24 h were higher than at 6 h." (PMID 26912204, 2016). "It is noteworthy that, among the proliferative response related genes, there is a synergism with the highly induced chemokines: the colony stimulating factor 3, specific for neutrophils, is sevenfold upregulated immediately after infection." (PMID 24812617, 2014).
infection (continued). "The CSF3 gene was also significantly up-regulated in the middle and late stages of infection." (PMID 39026675, 2024). "In addition, CSF3, related to immune cell activity regulation, was significantly up-regulated in the late stage of infection." (PMID 39026675, 2024). "The cytokines TNF-α, IL-6, IL-18, IFN-β, IFN-γ, and CSF3 produced by macrophages play important roles in the protection again pathogens by promoting phagocytosis and mediating the recruitment and activation of effector immune cells into the site of infection." (PMID 37431006, 2022). "The role of G-CSF and G-CSFR in regulating blood neutrophil counts was clearly demonstrated in Csf3-/- (G-CSF deficient) and Csf3r-/- (G-CSFR deficient) mice in response to an infection." (PMID 36618429, 2022). "Our study showed that CSF3 (Myelomonocytic growth factor) increased in the bursae of IBDV-infected chickens at 1 day post infection, which could induce leukotrienes and exert anti-HIV-1 effects." (PMID 28486945, 2017). "Similarly, CSF3, that may reduce Salmonella shedding upon infection in pigs, was less expressed in HS the day of infection." (PMID 36629432, 2023). "Among the upregulated genes there are genes that belong to infection-associated inflammatory Acute Phase proteins (APPs), such as Serum amyloid A1 (SSA1, FC = 1599) and A2 (SSA2, FC = 49), colony stimulating factor CSF2 (FC = 1316) and CSF3 (FC = 234), as well as Ceruloplasmin (CP; FC = 46.49)." (PMID 35531332, 2022). "In addition, the induction of systemic responses via the acute-phase response and increasing serum concentrations of CSF3 and CSF2 is linked to an increase in neutrophil and macrophage numbers at the site of infection in mice, and is regulated by IL-17 amongst other cytokines." (PMID 31998322, 2019). "At 24 h after infection, the following genes were upregulated in infected macrophages transfected with the let-7e inhibitor compared to macrophages transfected with NC: Tlr7, Ly96/MD-2, Casp8, Map3k1, Mapk8, Ptgs2/Cox2, Csf 3/GCSF, and the ubiquitin-conjugating enzyme E2N (Ube2n)." (PMID 30555476, 2018). "Signaling by CSF3 through the CSF3R contributes in an important manner to neutrophil homeostasis, but especially in the context of inflammation, infection and their respective resolution." (PMID 41154433, 2025). "Sharp differences appeared in the levels of Csf3 protein in the lung, which increased 49-fold (p = 0.0015, ANOVA) post-infection in K-RasLA1 mice relative to a 5-fold increase (p = 0.61, ANOVA) in mock-infected wild-type mice." (PMID 39338937, 2024). "ALKBH5 knockdown increased the levels of the IL-1β, CSF3, TGM2, and SRC transcripts during infection by P. aeruginosa, C. diphtheriae, WT HSV-1, or the ICP34.5 mutant virus." (PMID 36625590, 2023). "The strongest responders to infection were cytokines CSF3, also called granulocyte colony-stimulating factor (G-CSF), and IL17C, and the antimicrobial peptide beta defensin-2 (DEFB4)." (PMID 34006652, 2021). "This is an expected reaction upon infection and responses with several of these chemokines and cytokines have also been monitored upon Eimeria infection in chickens, e.g. CCL4, IL-8, IL-1β and CSF3." (PMID 33536090, 2021). "infection, whereas the corresponding early responding genes in SCC cells were IL10, IL1β, IL1α, TNF, CXCL10, CXCL1, HBEGF, IL6, and CSF3." (PMID 31912662, 2020). "The release of select inflammatory proteins (IL6, IL8, CSF3, IL1β, CXCL10, and ICAM1) into the culture medium of HEKs and SCC cells following infection with C. t." (PMID 31912662, 2020). "The infection of WT mice with C. rodentium led to an increased production of the innate cytokines IL-6, TNF-α, and CSF3 (also known as G-CSF), as well as the prototype Th1 cytokine IFN-γ, and the Th17 cytokine IL-17." (PMID 29922289, 2018). "Our results show a statistically significant increase in the expression of CSF3 and CXCL2 in KO compared to WT mice at 6 h post-infection." (PMID 30333823, 2018).
infection (continued). "We observed a clear signature of up regulated CSF3, as well as CXCL2 6 h post-infection genes in Ghrh−/−." (PMID 30333823, 2018). "In our study, MCP-1, TNF-α and CSF3 of WD infected PAM were all downregulated, when compared with KO infection, which is likely to increase S. zooepidemicus pathogenesis." (PMID 22567158, 2012). "Pro-inflammatory cytokines and chemokines, including TNF-α, CSF3 and CCL4, were upregulated in both infection groups, alongside genes involved in immune cell adhesion and inflammatory responses (SELE), as well as stress response mediators such as HSP70 and PNLIPRP3." (PMID 41435987, 2025). "Furthermore, the top six DEGs, including CSF3, CCL2, CCL7, IL6, CXCL11, and CXCL10, were all upregulated after infection at P3." (PMID 34026883, 2021). "TNF (degree = 11), CXCL2 (degree = 8), CSF3 (degree = 5), HIST2H2BE (degree = 11) and FGF2 (degree = 10) family proteins were activated and had a strong interaction, indicating that cells had a strong inflammatory response after infection." (PMID 34632719, 2021). "It has been reported that the granulocyte colony-stimulating factor (CSF3) was the most upregulated gene after SARS-CoV2-infected genes, suggesting that CSF3 is a significant target after infection and it may also be a potential target for drug therapy." (PMID 33551833, 2020). "Remarkably, CSF2 (encoding granulocyte-macrophage colony-stimulating factor), IL-6 (interleukin-6), IL-12B (interleukin-12 subunit beta), CSF3 (granulocyte colony-stimulating factor), and TNF (tumor necrosis factor) were extremely highly expressed upon infection with WT V. vulnificus (log2 FC > 8)." (PMID 32817457, 2020). "In those mice, a significant decrease in infection-induced plasma CSF3 levels and related lack of emergency granulopoiesis from the bone marrow was observed." (PMID 32038494, 2019). "Expression of an array of cytokines (CSF3 [G-CSF], IFNγ, IL-1β, IL-6, IL-22, IL-17A, and IL-10), chemokines (CCL20, CXCL2 and CXCL9) and receptors (CD40) known to be involved in the regulation of S. pneumoniae inflammatory response was measured at 0, 6, 24, and 48 h post-infection." (PMID 30333823, 2018). "On the other hand, early after infection, compared to noninfected pigs, expression of GNLY and CSF3 but also that of TLR1, 3, and 6, key players of innate response development, was downregulated only in HS pigs." (PMID 36629432, 2023). "ELISA analyses revealed that CSF3, IL-1β, and IL-6 proteins were induced by EV71 or R848 (a TLR7 agonist) as a stimulus control, but not by mock-infection or UV-inactivated EV71, in THP-1, macrophages, and human PBMCs." (PMID 28854257, 2017). "The infection of MDMs with Mtb opsonized with hSAA-1, compared to the infection with nonopsonized bacilli, led to at least a 2-fold increase in the concentrations of CSF2, CSF3, IL-1α, IL-1β, IL-6, IL-12, CCL15, and TNF-α with the most potent 10-fold increase observed for CCL5." (PMID 37781389, 2023).
cancer (621 papers, 1997 to 2026). A tumor composed of atypical neoplastic, often pleomorphic cells that invade other tissues. "Here, we analyzed the structure of the CSF3 gene encoding the G-CSF protein to delineate the mechanism of G-CSF production by the cancer cells." (PMID 37746465, 2023). "Of those modulated genes, SPP1, IL1RN, IL1A, TNFSF13B, OSM, and CSF3 had the most clinical relevance, as their high expression was associated with poor cancer patient overall survival." (PMID 31022845, 2019). "Neutrophils and cancer-associated adipocytes (CAAs) can secrete CSF3." (PMID 40185722, 2025). "CSF3 is a member of the CSF superfamily and is considered as a growth factor with the ability to stimulate the proliferation and differentiation of cancer cells." (PMID 36982170, 2023). "The activation of genes such as NR4A3, MET, ZEB1, CSF1, CSF2, CSF3, which can be involved in transcriptional dysregulation in cancer or hematopoietic cell lineage signaling pathways, can also be involved in cell differentiation." (PMID 37606991, 2023). "We explored the potential mechanism of GCSF (CSF3), GCSFR (CSF3R) and STAT3 in the pathogenesis of GBM from the dataset of patient samples of the TCGA Pan-Cancer Atlas database with the respective genetic alterations of GCSF (CSF3) 1.7%, GSCFR (CSF3R) 2.1% and STAT3 1.7% respectively." (PMID 38538691, 2024). "Among the DEPs involved in the IL17, Th17 cell differentiation and JAK-STAT signaling pathways, elevated levels of CSF3 and reduced CXCL6 were previously found in the serum of CRC patients, while our study also demonstrates their association with cancer-associated inflammation." (PMID 37228491, 2023). "Several studies have uncovered molecular pathways and immune responses in the colorectal TME, indicating that targeting CSF3 could be a potential strategy for cancer treatment." (PMID 38067251, 2023). "However, the large numbers of consistent results suggest that CSF3 signaling plays similar roles in both cancers." (PMID 33606788, 2021). "Moreover, 3D imaging of bone lesions from Csf3 KD cancer cells revealed a substantial reduction in vascular sprouting frequency and length." (PMID 34836954, 2021). "The mRNA expression of cytokines involved in neutrophil recruitment to cancer sites, such as colony‐stimulating factor‐2 (CSF‐2), CSF‐3 and chemokine (C‐X‐C motif) ligand 1 (CXCL1), was determined, and CSF‐2 and CSF‐3 were reduced and CXCL1 expression was increased in CT26‐mP2X7R cells." (PMID 32735377, 2020). "CSF3 codes granulocyte-colony stimulating factor (G-CSF), a glycoprotein that stimulates the bone marrow to produce granulocytes and stem cells and release them into bloodstream, and is widely used in chemotherapy to enhance the immunity of cancer patients." (PMID 30973327, 2019). "Protein-protein interaction (PPI) analysis identified the interactions among these proteins, including the pro-inflammatory cytokines IL-6, IL-8, and Colony Stimulating Factor 3 (CSF3), which have been previously implicated in the development of cancer cachexia." (PMID 31455042, 2019). "Some of cancers in animals and humans, such as 4T1 cancer cells, are known to produce a large amount of granulocyte colony‐stimulating factors (G‐CSF/Csf3) which can stimulate myeloproliferation, such as myeloid‐derived suppressor cells (MDSCs) leading to a poor recipient prognosis." (PMID 26923183, 2016). "Our gene expression analysis also revealed up-regulation of CSF-2 (GM-CSF) in macrophages grown as co-culture with cancer cells and CSF-2, CSF-3 and CSF1R up-regulation in cancer cells grown together with macrophages." (PMID 22353646, 2012). "Furthermore, monocyte dynamics are reprogrammed in cancer patients through alterations in systemic cytokines, such as colony-stimulating factor 1 (CSF1), CSF2 and CSF3." (PMID 41444555, 2025).